TRPA1 (transient receptor potential cation channel subfamily A member 1)
Diseases named in the same sentence as TRPA1 in open-access papers (continued):
Sharing a sentence is not in itself a finding about the gene and the disease.
Airway obstruction (2 papers, 2019 to 2021). Obstruction of conducting airways of the lung. "An important finding in this study is that simultaneous blockade of TRPV1 and TRPA1 results in a synergistic inhibitory effect on cough and airway obstruction." (PMID 31170972, 2019). "Furthermore, our data show that combined blockade of both TRPV1 and TRPA1 channels results in greater degree of inhibition of both cough and airway obstruction." (PMID 31170972, 2019). "Our next question was whether TRP channels, specifically TRPV1 and TRPA1, were involved in the BK sensitization of cough and airway obstruction." (PMID 31170972, 2019). "Our findings show that central BK administration sensitizes cough and enhances airway obstruction via a B2 receptor/TRPV1 and/or TRPA1 channels which are coupled via metabolites of COX and/or 12-LOX enzymes." (PMID 31170972, 2019). "In summary, our data show that centrally administered BK activates B2 receptors which results in enhanced citric acid-induced cough and airway obstruction via the sensitization of TRPV1 and/or TRPA1 channels through metabolites of COX and/or 12-LOX." (PMID 31170972, 2019). "Collectively, our findings point to an important role for BK, via B2 receptors, in the central sensitization of airway responses namely cough and airway obstruction and further identify TRPV1, TRPA1 and metabolites of COX and 12-LOX as key molecules in the sensitization process." (PMID 31170972, 2019). "The link between TRPV1 and TRPA1 activation and increased airway obstruction is not clear, However, multimodal activation of TRPV1 channels trigger increased spontaneous glutamate release within the nTS." (PMID 31170972, 2019). "In addition, combined blockade of TRPV1 and TRPA1 or COX and 12-LOX resulted in a greater inhibitory effect of both cough and airway obstruction." (PMID 31170972, 2019). "Furthermore, co-administration of submaximal doses of the TRPV1 and TRPA1 antagonists or the COX and 12-LOX inhibitors resulted in a greater inhibition of both cough reflex and airway obstruction." (PMID 31170972, 2019). "In addition to the effects on cough, our data show that blockade of both the TRPV1 and TRPA1 channels (by JNJ-17203212 and HC-030031, respectively) resulted in a significant inhibition of the BK-induced enhancement of airway obstruction by 77 and 80%, respectively." (PMID 31170972, 2019). "Based on the fact that BK-enhanced cough and airway obstruction were dependent on both TRPV1 and TRPA1 channels activation, in our next experiments we assessed whether combined treatment with sub-maximal doses of the TPRV1 and TRPA1 antagonists would achieve greater inhibitory effects." (PMID 31170972, 2019).
allergic conjunctivitis (2 papers, 2019 to 2024). "Compared to wild-type animals, TRPA1 deficient mice show fewer symptoms in a model of allergic conjunctivitis." (PMID 31547502, 2019). "Recently, it was suggested that TRPA1 might also be involved in allergic conjunctivitis." (PMID 31547502, 2019). "They concluded that a TRPV1 antagonist rather than a TRPA1 antagonist may ameliorate allergic conjunctivitis by suppressing the Type 2 helper T cell cytokine response in draining lymph nodes." (PMID 39195219, 2024).
astrocytoma (2 papers, 2010 to 2023). "Using paraffin immunohistochemistry, TRPV1 and TRPA1 protein expression was found in 62% of the WHO grade II astrocytomas, 37.5% of the anaplastic astrocytomas (WHO grade III), and 16.3% of GBM cases." (PMID 37240443, 2023). "Transcripts exhibiting significant under expression in trisomic BG01V APCs and CCF-STTG1 astrocytoma cells relative to diploid H9 APCs include several markers of normal differentiated astrocytes, including TRPA1, GABRA2, BDNF, BDKRB1 and BDKRB2." (PMID 20423517, 2010).
autoimmune disease (2 papers, 2023 to 2025). A disorder resulting from loss of function or tissue destruction of an organ or multiple organs, arising from humoral or cellular immune responses of the individual to their own tissue constituents. "Therefore, modulation of TRPA1 signaling by CBG might be used to modulate disease activity in RA as this autoimmune disease is accompanied by oxidative stress and subsequent activation of pro-inflammatory pathways." (PMID 36614296, 2023).
cervix cancer (2 papers, 2022 to 2024). "A number of studies also showed that TRPA1 agonist AITC negatively affects the cell proliferation of breast, bladder and cervix cancer cells." (PMID 35163843, 2022). "This conclusion is supported by the viability-decreasing effect of AITC on CHO cells not expressing the TRPA1 channel and the similar action of AITC in other cancer types 9 HepG2 human hepatocellular carcinoma cells and breast, bladder, and cervix cancer cells." (PMID 38612571, 2024).
chronic rhinosinusitis (2 papers, 2021 to 2026). Chronic form of sinusitis. "Immunohistochemistry showed positive TRPA1 signal in infiltrating macrophages in human ectopic endometrial tissue, inflamed colon of IBD patients, human oral submucosa, and nasal polyps of chronic rhinosinusitis patients." (PMID 34768891, 2021).
ciguatera (2 papers, 2015 to 2017). "Ciguatoxins may confer cold sensitivity to a subpopulation of cold‐insensitive Nav1.8/TRPA1‐positive primary afferents, which could underlie the cold allodynia reported in ciguatera." (PMID 26454262, 2015). "Activation of TRPA1 may also mediate pruritus, a prominent symptom associated with ciguatera." (PMID 26454262, 2015). "We recently established an animal model of ciguatera based on the intraplantar administration of P-CTX-1 in mice and showed that ciguatoxin-induced cold allodynia is mediated through TRPA1-expressing C-fibres and involves NaV1.89." (PMID 28225079, 2017).
Constipation (2 papers, 2023). Infrequent or difficult evacuation of feces. "Furthermore, paeoniflorin has the ability to alleviate loperamide-induced constipation by mediating G-protein-coupled bile acid receptor/TRPA1 signaling." (PMID 36992686, 2023). "To further explore the mechanism for the 5-HT-mediated treatment of constipation, we studied TRPA1." (PMID 36992686, 2023).
demyelinating disease (2 papers, 2023). A broad group of disorders that affect the myelin sheaths that cover the neurons. "A possible role of TRPA1 has been reported in models of MS, and in a mouse model of the demyelinating disease induced by cuprizone, where the activation of astrocyte expressing TRPA1 elicits the release of pro-inflammatory mediators contributing to oligodendrocyte apoptosis." (PMID 37296632, 2023).
Dry skin (2 papers, 2021 to 2022). Skin characterized by the lack of natural or normal moisture. "Our results revealed that the mRNA expression levels of Trpa1 (t8 = 4.798, P = 0.0014), Trpv1 (t8 = 3.258, P = 0.0116), and Trpv4 (t8 = 4.297, P = 0.0026) significantly increased in the DRGs of dry skin-induced chronic itch model." (PMID 35095413, 2021).
endotoxemia (2 papers, 2022 to 2023). "Compound 36, a potent dual PDE4/7 inhibitor and TRPA1 antagonist, exerted strong anti-TNF-α activity in vivo in lipopolysaccharide (LPS)-induced endotoxemia, which was manifested by a significant reduction in the maximum plasma concentration of TNF-α by 90.2%." (PMID 35930193, 2022). "Together, these data establish that vagus TRPA1+ nociceptors are necessary and sufficient to stimulate a reflex anti-inflammatory response via afferent vagus nerve fiber signaling and inhibit TNF production during endotoxemia." (PMID 36650454, 2023).
Erythema (2 papers, 2019 to 2025). Redness of the skin, caused by hyperemia of the capillaries in the lower layers of the skin. "Dysregulation of TRP channel activity, particularly TRPV1 and TRPA1, has been shown to induce neurogenic inflammation, erythema, and irritation, which are hallmark features of skin toxicity." (PMID 41373824, 2025). "At day 5, but not day 3, the total PSI scores of TRPA1 KO mice (P < 0.001) were consistently decreased in TRPA1 KO (vs WT) mice, which were reflected in individual scores of scales (PSI‐S) (P < 0.01), induration (PSI‐I) (P < 0.001) and erythema (PSI‐E) (P < 0.05)." (PMID 31111624, 2019).
experimental autoimmune encephalomyelitis (2 papers, 2021 to 2023). An autoimmune demyelinating disease of the central nervous system that is produced experimentally in animals by the injection of homogenized brain or spinal cord in Freund's adjuvant. "Transient receptor potential ankyrin 1 (TRPA1) was involved in neuropathic nociception in a model of PMS induced by experimental autoimmune encephalomyelitis (PMS-EAE), and TRPA1 activation causes periorbital and facial nociception." (PMID 34451927, 2021).
gastric cancer (2 papers, 2022 to 2024). A primary or metastatic malignant neoplasm involving the stomach. "Overexpression of certain calcium ions such as TRPA1 and TRPC5 promotes chemoresistance in gastric cancer cells." (PMID 38370477, 2024).
gram-negative bacterial infections (2 papers, 2016 to 2020). Infections caused by bacteria that show up as pink (negative) when treated by the gram-staining method. "Only recently, TRPA1 was ascribed a crucial role in the context of gram-negative bacterial infections." (PMID 27356469, 2016).
head and neck cancer (2 papers, 2017 to 2022). A primary or metastatic malignant neoplasm affecting the head and neck. "Moreover, oesophageal and head-and-neck cancer patients also overexpress TRPV1 and TRPA1 and these cancers are more promising targets for TRPV1 or TRPA1 agonist therapy." (PMID 35614079, 2022).
hematoma (2 papers, 2019 to 2023). A hematoma is a collection of blood from a vascular structure into an extravascular space. "The nonselective TRPA1 cation channel was involved in myelin injury after ICH, and inhibition of TRPA1 during the acute phase of ICH could ease the peri-hematoma white matter injury, nerve impulse conduction disorder and motor dysfunction in the mice." (PMID 31057367, 2019).
hemorrhagic cystitis (2 papers, 2017 to 2021). Inflammation of the bladder resulting in bloody urine. "Hypersensitivity of the abdomen after ifosfamide-induced hemorrhagic cystitis was lessened by systemic application of the TRPA1 antagonist HC-030031." (PMID 28824373, 2017). "Furthermore, the bladder toxicity induced by CYP has been attributed to its metabolite acrolein, which, if not scavenged, damages the bladder, leading to hemorrhagic cystitis and TRPA1-dependent visceral pain." (PMID 34976095, 2021).
hemorrhagic stroke (2 papers, 2019 to 2023). A stroke caused by a bleed on the brain. "However, we didn’t observe any differences in survival or other outcomes between control and Trpa1-ecKO mice, suggesting that interventions targeting TRPA1 channels in the clinical setting may have minimal impact on hemorrhagic stroke patients." (PMID 36793787, 2023). "Therefore, we hypothesized that TRPA1 channel activity is increased during hemorrhagic stroke." (PMID 36793787, 2023). "The effects of endothelial cell TRPA1 channels on the incidence or severity of hemorrhagic stroke events have not been previously reported." (PMID 36793787, 2023). "Interestingly, the current study shows that not only does this protection not extend to cases of hemorrhagic stroke, but instead, TRPA1 channel activity appears to exacerbate the size of the hemorrhagic lesions." (PMID 36793787, 2023).
hepatocellular carcinoma (2 papers, 2024). A malignant tumor that arises from hepatocytes. "Allyl isothiocyanate (AITC), a dietary phytochemical compound found in some cruciferous vegetables and also a selective and potent agonist of TRPA1, was shown some years ago to decrease the viability and angiogenesis in hepatoma cells." (PMID 39770499, 2024).
Hyperkeratosis (2 papers, 2019 to 2022). Hyperkeratosis is a histopathological term defining a thickened stratum corneum and may be present in many different skin conditions, with many possible overlaps. "In wild type and TRPA1 KO mice, however, enhanced skin thickness and hyperkeratosis blocked further increase of drug penetration at the late phase (96 h)." (PMID 35457056, 2022). "As expected, hyperkeratosis, parakeratosis and epidermal hyperplasia were present in WT mice but subjectively reduced in TRPA1 KO mice after 5 days of topical IMQ treatment." (PMID 31111624, 2019).
inflammatory skin disorders (2 papers, 2017 to 2021). "In conclusion, these findings point to an inflammatory role for TRPA1 in keratinocytes and present TRPA1 as a potential drug target in inflammatory skin diseases." (PMID 33805042, 2021). "Intriguingly, the anti-inflammatory drugs cyclosporine, tacrolimus and dexamethasone (which are all used to treat inflammatory skin diseases) significantly inhibited TNF-induced TRPA1 upregulation." (PMID 33805042, 2021). "TRPA1 may also be involved in some inflammatory skin disorders, as neurogenic inflammation is known to play a role in cutaneous inflammation." (PMID 33805042, 2021).
kidney (2 papers, 2021 to 2024). "TRPA1 was previously identified as a prostate-associated gene and acts as a modulator of angiogenesis, so it is more likely expressed in cells surrounding the tumoral tissue." (PMID 39770499, 2024). "However, renal tubular epithelial TRPA1 is an oxidative stress sensor which mediates hypoxia–reoxygenation injury in vitro and ischaemia–reperfusion-induced kidney injury in vivo through MAPKs/NF-kB signalling." (PMID 33810314, 2021).
metabolic syndrome (2 papers, 2021 to 2023). A cluster of metabolic risk factors for CARDIOVASCULAR DISEASES and TYPE 2 DIABETES MELLITUS. "Consequently, further studies involving specific TRPA1 modulators need to be designed to target metabolic syndrome involving NPDs." (PMID 34912298, 2021).
metastatic melanoma (2 papers, 2021 to 2025). A melanoma that has spread from its primary site to another anatomic site. "Using a dataset of CD8+ T cells isolated from metastatic melanoma patients, we found that TRPA1 reduction correlates with several immunological pathways." (PMID 34041030, 2021). "Corroborating our experimental data, we discovered that TRPA1 is negatively correlated with several immunological related pathways in CD8+ T cells isolated from metastatic melanoma patients." (PMID 34041030, 2021).
non-small cell lung carcinoma (2 papers, 2022). A group of at least three distinct histological types of lung cancer, including non-small cell squamous cell carcinoma, adenocarcinoma, and large cell carcinoma. "Existing literature shows that TRPA1 is increasingly expressed in non-small cell lung cancer patients." (PMID 36090899, 2022). "The finding indicates that TRPA1 may serve as a potential prognosis marker and facilitate the search for the target drug to inhibit the progression of non-small cell lung cancer." (PMID 35887116, 2022). "TRPA1 has been observed to be overexpressed in the MSCs of human lung cancer tissues, which might be related to the poor prognosis of non-small cell lung cancer." (PMID 35887116, 2022).
oedema (2 papers, 2014 to 2016). "of the TRPA1 agonist, AITC (10 nmol per paw), induced paw oedema that peaked at 60 min after injection." (PMID 25484020, 2014). "In the present study we showed that TRPA1 does not have a role in acute carrageenan-induced paw oedema, mechanical and thermal hypersensitivity." (PMID 26746673, 2016).
oral ulcerative mucositis (2 papers, 2017 to 2021). "In the present study, hypertonic stimulation-induced and AITC-induced Ca2+ responses were suppressed by long-term preincubation with Tmc, suggesting that TRPA1 suppression following the long-term effect of Tmc on peripheral nerves inhibits oral ulcerative mucositis-induced mechanical allodynia." (PMID 34830488, 2021). "Co-expression and synergic interactions between TRPV1 and TRPA1 were also observed in nociceptive neuronal fibers in rats with oral ulcerative mucositis–induced spontaneous pain following treatment with 5-fluorouracil (5-FU), and the TRPV1 but not TRPA1 was activated by 5-FU treatment." (PMID 29326595, 2017).
osteoporosis (2 papers, 2023 to 2024). A condition of reduced bone mass, with decreased cortical thickness and a decrease in the number and size of the trabeculae of cancellous bone (but normal chemical composition), resulting in increased fracture incidence. "It is noteworthy that the TRPA1 antagonist significantly improved cold sensitivity, suggesting a role for TRPA1 in osteoporosis bone pain." (PMID 37238956, 2023).
ovarian carcinoma (2 papers, 2022 to 2024). A malignant neoplasm originating from the surface ovarian epithelium. "Moreover, although the samples had a higher TRPA1 expression in breast, prostate and ovarian cancer tumours, the metastatic tissues recovered almost entirely under the initial values from the non-tumoral tissues." (PMID 39770499, 2024).
Photophobia (2 papers, 2019 to 2024). Excessive sensitivity to light with the sensation of discomfort or pain in the eyes due to exposure to bright light. "A rapid-onset and injury-free mouse model of photophobia was developed following intranasal injection of the TRPA1 activator, umbellulone." (PMID 39390364, 2024).
pulpitis (2 papers, 2019 to 2025). Inflammation of the dental pulp. "If TRPA1 is expressed in odontoblasts (which remains questionable), this channel may contribute to pain in response to chemical substances generated during pulpitis." (PMID 41516061, 2025). "Taken together, these observations imply that during pulpitis neuronal TRPA1 may play a role in the neurogenic inflammatory reaction." (PMID 41516061, 2025). "Furthermore, TRPA1 expression on myelinated nerve fibers was upregulated in teeth with signs of pulpitis." (PMID 30691193, 2019). "Pulpitis elevates endogenous TRPV1 and TRPA1 agonists, while inflammatory mediators sensitize TRP channels, amplifying pain." (PMID 41516061, 2025). "In addition, upregulation of TRPA1 and TRPV4 in the pulpal nerve fibers is observed in teeth with signs of pulpitis." (PMID 30691193, 2019).
retinal ischemia (2 papers, 2024). A ischemic disease that involves the retina. "Overall, this research offers insights into the potential mechanisms underlying neuroprotection during retinal ischemia and identifies TRPA1 as a promising target for future neuroprotective interventions in this condition." (PMID 38256192, 2024). "Cannabinoid receptors and transient receptor potential ankyrin (TRPA1) channels were also explored in the context of retinal ischemia, a condition marked by an inadequate blood flow to the retina, often associated with vision loss and a lack of effective treatments." (PMID 38256192, 2024).
rhinitis (2 papers, 2016 to 2021). An inflammation of the mucous membrane lining the nose, usually associated with nasal discharge. "In rhinitis patients, TRPA1 mRNA levels are increased and a decreased threshold for neuronal activation in response to the TRPA1 agonist allyl isothiocyanate was observed." (PMID 33738577, 2021).
scabies (2 papers, 2024 to 2025). "Overall, our findings suggest that TRPA1 may be a previously unrecognized target for improving the control of MRSA skin infections and elucidating some of the molecular mechanisms of TRPA1 modulation." (PMID 39337422, 2024). "Two prior studies have reported increased expression of PAR-2, tryptase, TSLP, periostin, TRPA1, TRPV1, and IL-31 in scabies lesions." (PMID 41325491, 2025). "Even though increased expression of TRPA1 has been detected in one study, involvement of MRGPRX2 in scabies itch is not explored." (PMID 41325491, 2025).